CSF1 (colony stimulating factor 1)
Diseases named in the same sentence as CSF1 in open-access papers (continued):
Sharing a sentence is not in itself a finding about the gene and the disease.
tumor (1,744 papers, 1996 to 2026). "This discovery led to the development of targeted systemic therapies aimed at interrupting the CSF1/CSF1R (Receptor) signaling axis responsible for tumor proliferation and the associated inflammatory microenvironment." (PMID 41523664, 2026). "The EVs associated protein CSF-1 have pivotal role in recruiting and polarizing tumor-associated macrophages (TAMs)." (PMID 40297849, 2025). "The expression of CD68 and CSF1 associated with tumor-associated macrophages (TAM) were significantly downregulated in NPRL2-treated samples." (PMID 39932765, 2025). "Univariate analysis revealed a significant association between a worse OS and pathological tumor depth, pathological stage, vascular invasion, number of M2 macrophages and TILs in HC, CSF-1 expression in HC, and HCR." (PMID 39488822, 2025). "Tumor-associated macrophage membranes (TAMMs) are employed to coat photosensitizer-loaded up conversion NPs (UCNPs) to attach colony-stimulating factor-1 (CSF-1), typically targeting native TAMs." (PMID 40225567, 2025). "In B‐cell lymphomas, decreased H3K27 acetylation suppresses FBXW7 expression, activates the NOTCH signaling pathway and downstream CCL2/CSF1, and promotes tumor cell proliferation and M2 polarization of tumor‐associated macrophages (TAMs)." (PMID 40761481, 2025). "Tumor‐associated macrophage infiltration in large numbers into ICI‐resistant malignancies is facilitated by the production of CSF1 and VEGF in tumor cells." (PMID 41403916, 2025). "SLC7A11 promotes HCC metastasis by increasing programmed death ligand 1 and colony-stimulating factor 1, and its high expression is linked to poor tumor differentiation and an advanced tumor-node-metastasis stage 25." (PMID 39744421, 2025). "For example, high baseline expression of CSF1R or its ligands (CSF1, IL-34) in the tumor microenvironment has been associated with better responses to CSF1R inhibitors." (PMID 40821795, 2025). "Forced expression of CSF-1 in tumor cells causes increased lung metastasis and an increase in macrophage infiltration to the primary tumor." (PMID 40646332, 2025). "Consider for example colony stimulating factor-1 (CSF-1), which is secreted by both cancer cells and tumor associated macrophages (TAMs)." (PMID 40464993, 2025). "In some cancers, high CSF-1 expression is associated with a poor prognosis, and inhibition of the CSF-1/CSF-1R pathway increases anti-tumor activity." (PMID 39488822, 2025). "In these settings, regorafenib is thought to confer sensitivity to tumors by its ability to reduce tumor-associated macrophages by blocking the colony-stimulating factor 1 (CSF-1) receptors." (PMID 40710850, 2025). "Concomitantly, MSCs-derived CCL5 binding to CCR5 on breast cancer cells result in the secretion of CSF1, which in turn binds to the CSF1 receptor on MSCs to recruit tumor-associated immune cells." (PMID 40676710, 2025). "The upregulation of SLC7A11 induces the infiltration of tumor-associated macrophages (TAMs) and MDSCs by activating the colony-stimulating factor 1 (CSF1)/colony-stimulating factor 1 receptor (CSF1R) axis." (PMID 38397901, 2024). "Intratumoral CSF-1/CSF-1R signaling has been reported to play a key role in triggering the recruitment of tumor-associated macrophages leading to tumor growth and facilitating metastasis." (PMID 39186767, 2024). "Mechanistically, the loss of TF/mTORC2 function in tumor cell can reduce CSF1, a critical growth factor of M2-macrophage." (PMID 38191673, 2024). "Adding recombinant CCL2 and CSF1 proteins reversed the inhibition of macrophage M2 polarization, recruitment and tumor proliferation phenotypes caused by AS‐99 treatment." (PMID 39377228, 2024). "IL-1β-induced excessive cystine transport protein-SLC7A11 enhances the expression of PD-L1 and colony-stimulating factor 1, and promotes tumor-associated macrophage and MDSC infiltration, therefore leading to HCC metastasis." (PMID 38466483, 2024).
tumor (continued). "SLC7A11, a member of the amino acid transporter SLC7 family, is induced by IL‐1β to upregulate PD‐L1 and CSF1 through αKG/HIF1α axis, leading to infiltration of tumor‐associated macrophages and myeloid‐derived suppressor cells and promoting metastasis of HCC." (PMID 39041652, 2024). "CSF1 in the TME is mainly derived from tumor cells and tumor-associated fibroblasts (TAFs), and studies based on spatial transcriptomics have also confirmed the co-localization of macrophages with these two types of cells." (PMID 38279145, 2024). "For example, using C–C chemokine 2 (CCL2) to block the recruitment of tumor-associated macrophages/microglia, or the colony-stimulating factor-1 (CSF-1R) inhibitor to impair the survival of macrophages/microglia." (PMID 38238749, 2024). "TAM-derived EGF then binds to the EGF receptor on tumor cells, leading to increased CSF1 production and activation of pathways associated with migration." (PMID 39555068, 2024). "The selective removal of tumor-associated macrophages was achieved by the intratumoral injection of Anti-CSF1 every 3 days, and Rat IgG was employed as the isotype control." (PMID 36959204, 2023). "The monocytes in the TME differentiate under the influence of IL-6 and CSF-1 into macrophages, specifically tumor-associated macrophages (TAMs)." (PMID 37736898, 2023). "Tumor-derived CSF-1 can suppress the migration of monocytes by causing cancer-associated fibroblasts (CAFs) to stop producing HDAC2-mediated chemokines that attract monocytes." (PMID 37138860, 2023). "Basement membrane destabilization associated with the loss of FBLN2 contributes to increased cancer cell migration and invasion, and high expression of CSF1 and macrophage infiltration are associated with the tumor, node and metastasis (TNM) stage of CRC." (PMID 36845686, 2023). "The characteristics of tumor-associated M2 macrophages are orchestrated by the action of IL-4, IL-10, IL-13, macrophage colony-stimulating factor 1 (CSF-1), CCL2, or VEGF-A." (PMID 38033495, 2023). "Here, we have demonstrated that the expression of Notch3 was positively associated with the level of soluble tumor-derived chemotactic factors, such as CSF1, CXCL12 and CCL2, which are chemotactic stimulus for macrophage recruitment." (PMID 36647017, 2023). "We demonstrated that FSTL1 inhibited M2-like tumor-associated macrophage recruitment toward the lungs by suppressing CSF1, VEGF-α, and TGF-β secretion in 4T1 cells." (PMID 37238210, 2023). "CSF1 is a major regulator of TAM recruitment to the tumor microenvironment that has been linked to poor prognosis and increased tumor invasiveness in several cancer types." (PMID 37505292, 2023). "Ruxolitinib upregulated expression of Csf1, widely associated with tumor promoting phenotype of macrophages." (PMID 37005447, 2023). "Colony-stimulating factor-1 (CSF1), also known as macrophage colony-stimulating factor, acts as a key cytokine in the production, recruitment, and activation of tumor-associated macrophages (TAMs) by binding with CSF1 receptor tyrosine kinase (CSF1R)." (PMID 37097499, 2023). "Beyond its antiangiogenic activity, regorafenib is able to reduce tumor-associated macrophages (TAMs) through the inhibition of the colony-stimulating factor 1 (CSF1) receptor, as demonstrated in tumor models." (PMID 37958363, 2023). "In the cancer setting, high levels of its ligand CSF-1 lead to tumor-associated macrophage recruitment and to polarization toward a tumor-supporting phenotype." (PMID 37637207, 2023). "To further investigate the role of macrophages in cSERPINE2-induced carcinogenesis, we constructed the Csf1op/op mice that lack macrophages with mutated macrophage colony stimulating factor 1 (Csf1) and then constructed orthotopic tumor xenograft models." (PMID 36797769, 2023). "Strong chemotactic sensitivity to CSF-1 (large values of χcm) can cause the macrophages to cluster around the last tumour cells to be eliminated." (PMID 36972297, 2023).
tumor (continued). "It was shown that increased expression of CSF-1 was one of the characteristics of increased tumor aggressiveness and was associated with poor prognosis of cancer patients." (PMID 36419877, 2022). "When CSF-1/CSF-1R is activated, tumor-associated macrophages (TAMs) secrete growth factors that contribute to tumor growth or metastasis, leading to a higher rate of recurrence." (PMID 35000616, 2022). "Among several cytokine and cytokine receptors, the colony-stimulating factor-1 (CSF-1) secreted by tumor cells interacts with various immune cells in the environment, particularly tumor-associated macrophages (TAM)." (PMID 35735443, 2022). "CSF-1R act as cell-surface receptors for the cytokines CSF-1 and IL-34 that are secreted by tumor cells and can cause the recruitment of M2-macrophages to support tumorigenesis." (PMID 35455743, 2022). "CircASAP1 controls the miR-326/CSF-1 pathway, which facilitates tumor-associated macrophage infiltration." (PMID 36672755, 2022). "Blockade of CSF1 or its receptor proved to be a selective approach to manipulating tumour‐associated macrophages in different types of cancer." (PMID 36433652, 2022). "Emerging data indicated that intratumor CSF-1/CSF-1R signaling can cause the recruitment of TAMs and the development of pro-tumor inflammatory environment, thereby leading to tumor growth and metastasis." (PMID 35444953, 2022). "CSF1 primarily regulates the survival, proliferation, and differentiation of monocytes/macrophages, which sustains the protumorigenic functions of tumor-associated macrophages." (PMID 36320082, 2022). "In a Lewis lung carcinoma (LLC) mouse model, CSF-1/CSF-1R blockade was found to deplete intra-tumoural NK cells and increase tumour metastasis, due to a loss of the TAM-derived NK survival factor IL-15." (PMID 35020853, 2022). "Immunohistochemical analysis of Vav1 and CSF-1 expression of primary human lung tumors pointed to a strong link between these proteins, associated with to tumor grade." (PMID 35326399, 2022). "(b) CSF-1R: CSF-1R is a tyrosine kinase receptor that, when bound with its ligand CSF-1, not only promotes the migration of MDSCs but also can differentiate and expand myeloid cells into MDSCs and tumor-associated macrophages (TAMs)." (PMID 35628647, 2022). "The combination of a ketogenic diet with CSF-1 inhibition normalized tumor-associated macrophages and led to a profound improvement in survival in mice." (PMID 36428642, 2022). "Chemokines secreted by tumor cells, such as C-C Motif Chemokine Ligand 2, C-C Motif Chemokine Ligand 5, and colony stimulating factor 1, can recruit M2-type tumor-associated macrophages, and their abundance in TME correlates with a poor prognosis." (PMID 35720039, 2022). "Tumour-associated macrophages (TAMs) are easily polarised by tumour-cell-producing colony-stimulating factor-1 into an immunosuppressive M2-like phenotype." (PMID 35800366, 2022). "Tumor-associated M2 polarized macrophages (TAMs) promote tumor cell to bone metastasis through CCL2/CCR2 or colony-stimulating factor 1 (CSF1)/CSF1R signaling." (PMID 34831167, 2021). "Inhibition of the CSF-1/CSF-1R signaling axis has been the most thoroughly investigated mechanism to deplete tumor-associated macrophage populations." (PMID 33924237, 2021). "Although various targets have been explored to reprogram or deplete tumor-associated macrophages, inhibition of the colony stimulating factor 1 (CSF1) or C-C Motif Chemokine Ligand 2 (CCL2) signaling have been particularly reported." (PMID 34683931, 2021). "Blocking monocyte recruitment and the subsequent activation of tumor-associated macrophages (TAMs) via inhibition of CSF-1/CSF-1R is a novel immunotherapeutic strategy 94,95." (PMID 34158855, 2021). "Tumor-associated macrophages (TAMs) represent another early innate immune cell with key roles in tumor development, recruited by chemokines released by tumor cells and associated stroma in a colony-stimulating factor 1 (CSF-1)-CSF-1R-dependent manner." (PMID 34685652, 2021).
tumor (continued). "For instance, NCS1 and CSF-1 are associated with promotion of tumor aggressiveness and poor outcome in various cancer types." (PMID 33671266, 2021). "The goal of CSF-1/CSF-1R blockade is to reduce accumulation of immunosuppressive tumor-associated macrophages and MDSCs in the tumor microenvironment." (PMID 33537102, 2021). "Preclinical studies have shown that targeting CSF-1/CSF-1R signaling depletes tumor-associated macrophages by inducing apoptotic death, inhibits their recruitment from circulating monocytes, and induces M2–M1 polarization." (PMID 34830923, 2021). "Both cell-surface isoforms and secreted CSF1 can have a broad implication in the regulation of tumor-associated inflammatory responses." (PMID 33466385, 2021). "ALKBH3, a demethylase for m1A, promotes mRNA stability of CSF1, which regulates the density of tumor-associated macrophages and CD3+ T lymphocytes via its demethylation activity and leads to poor prognosis in breast cancer." (PMID 33741974, 2021). "Colony-stimulating factor 1 (CSF-1) is a potent chemoattractant that regulates the differentiation of monocytes into tumor-associated macrophages (TAMs), and its overexpression correlates with increased TAM infiltration and poor clinical outcomes." (PMID 33572835, 2021). "We also investigated macrophage cultures, whose gene expression upon polarisation with CSF1 was found to resemble that of tumour-associated macrophages from PDAC tumours." (PMID 34561461, 2021). "In line with this, it is highly likely that certain tumor cells capable of forming osteolytic bone metastasis recruit not only tumor-associated macrophages, but monocytes/osteoclast precursors via the secretion of CSF-1 into the tumor microenvironment." (PMID 32637413, 2020). "Tumor-associated macrophages (TAMs) massively infiltrate around tumor cells due to action of colony-stimulating factor 1, VEGF, and certain chemokines." (PMID 32850400, 2020). "It has been already shown that tumor-associated macrophages release tumor-derived CSF-1 and macrophage-derived EGF through a paracrine manner, further promoting therapy resistance." (PMID 33262705, 2020). "Considering that SRC acts downstream the CSF-1 pathway and given that increased serum levels of this cytokine associate with higher aggressiveness of different tumor types, this study also analyzed the serum levels of CSF-1 in MM patients." (PMID 32664483, 2020). "The analysis of clinical tumour samples showed a positive association between up‐regulated circASAP1 and tumour‐associated macrophages (eg CSF‐1 and MAPK1)." (PMID 32281724, 2020). "The CSF-1/CSF-1R axis plays a key role in macrophage differentiation, proliferation and survival, especially for M2-like tumor-associated macrophages (TAMs)." (PMID 31438996, 2019). "We found that high CSF-1 expression in UTUC tissues was significantly associated with tumor stage (P < 0.001), distant metastasis (P = 0.006), recurrence (P = 0.003), and cancer death (P = 0.005)." (PMID 31565097, 2019). "Univariate analysis also demonstrated that both tumor stage and CSF-1 expression were associated with cancer-specific survival." (PMID 31565097, 2019). "Overexpression of CSF-1 is associated with this rare tumor type and the disease itself is linked to significant reactive inflammation in the tumor environment, suggesting a role of CSF-1 targeted therapy." (PMID 31439034, 2019). "A high level of CSF-1 or CSF-1R expression in the tumor or peri-tumor tissue has been associated with poor patient survival in lymphoma, breast cancer, and hepatocellular carcinoma." (PMID 31878087, 2019). "In the case of immunosuppressive cytokines, we describe strategies to block the activity of tumour necrosis factor-alpha (TNF-α), TGF-β and cytokines that nurture tumour-associated myeloid cells, such as colony-stimulating factor-1 (CSF-1)." (PMID 30413827, 2019).
tumor (continued). "Tumor-associated macrophages (TAMs) perform pro-angiogenic effects through their response to colony-stimulating factor-1 (CSF-1) and Ang2; meanwhile, TAMs produce VEGF-A and Wnt7B." (PMID 31835465, 2019). "Tumors become infiltrated with BM-DMs that are attracted to the tumor via the secretion of damage associated molecular patterns (DAMPs) and specific macrophage chemoattractants CSF-1 and chemokine C-C motif ligand 2 (CCL2)." (PMID 30356656, 2018). "Epithelial cancer cells and stromal cells do just this–they secrete growth factors and cytokines such as macrophage colony-stimulating factor 1 (CSF-1) to recruit macrophages, converting their phenotype into tumor-associated macrophages (TAMs)." (PMID 29996539, 2018). "Namely, tumor-associated ECs express and release IL-6, jointing with CSF-1 in the microenvironment, induces HIF-2α-dependent arginase-1 expression through activation of PPAR-γ, leading to macrophage alternative polarization and GBM progression." (PMID 29422647, 2018). "Calculation of the ESTIMATE score, to infer tumor purity, and of the stromal score revealed that CSF-1 and CSF-1R are strongly linked to the stromal compartment in all subtypes." (PMID 29796177, 2018). "We find that, in a set of transplant and spontaneous cancer models, tumor cells secrete the cytokine CSF-1, which induces the NKG2D ligand RAE-1δ on tumor-associated macrophages via a CSF-1R-PI3Kα-dependent signaling pathway." (PMID 29757143, 2018). "Although DIPG tumor cells produce CSF1, a cytokine associated with the M2, pro-tumorigenic phenotype, we found that DIPG-associated macrophages do not fit neatly into an M1 or M2 classification." (PMID 29954445, 2018). "Increased CSF‐1 was associated with increased tumour‐associated macrophages (TAMs), which were immunosuppressive." (PMID 30442705, 2018). "MMTV-PyMT mice carrying a homozygous mutation in the colony-stimulating factor-1 (Csf1) gene (Csf1op/op) recruit fewer tumor-associated macrophages (TAMs) than Csf1-proficient mice." (PMID 29766399, 2018). "Collectively, these data provide decisive evidence that production of CSF-1 by tumor cells in vivo drives RAE-1δ expression on tumor-associated macrophages." (PMID 29757143, 2018). "Age, smoking, percentage of pockets ≥4 mm, number of manifest caries lesions, and presence of tumor were associated with CSF-1 levels." (PMID 28779164, 2017). "Accumulating evidence suggests that CSF-1 and its receptor, CSF-1R, are implicated in tumor development and progression." (PMID 28170411, 2017). "CSF-1 influences also the maturation of tumor-associated macrophages; in CSF-1 deficient animals macrophages remained more immature with lower expression of IL-1β, TNF-α." (PMID 28197019, 2017). "Tumor cells or tumor-associated stromal cells produce hematopoietic growth factors (CSF-1, GM-CSF, and IL-34) which increase the expansion of the monocyte-macrophage lineage." (PMID 28197019, 2017). "Studies involving TAM depletion in breast tumours using Csf1-null mutation displayed substantial reduction in angiogenic potential and tumour burden, suggesting that these macrophages are required for angiogenesis." (PMID 29065107, 2017). "Genetic loss of CSF1 results in significantly reduced metastasis and delayed tumor progression in breast and neuroendocrine tumor models." (PMID 28241846, 2017). "CSF1-deficient mice showed a 50% decrease in macrophage infiltration while neutrophil infiltration was increased during tumor progression in a mouse model of pancreatic islet cancer." (PMID 28769933, 2017). "In general, patients having tumours with a Th1 CTL cytokine profile have a better prognosis than those with a Th2 profile or a pattern of tumour-associated macrophages (TAM) infiltration via CSF1 recruitment." (PMID 28193698, 2017). "Small interfering RNA against CSF-1 caused decreased neuroblastoma tumor growth with less macrophage infiltration, lower MMP12 level, and angiogenesis." (PMID 28197019, 2017).